IDO1 (indoleamine 2,3-dioxygenase 1)
Diseases named in the same sentence as IDO1 in open-access papers (continued):
Sharing a sentence is not in itself a finding about the gene and the disease.
colon carcinoma (continued). "The expression of IDO1 in colon cancer tissues was higher than that in adjacent noncancerous tissues by IHC." (PMID 31391111, 2019). "Therefore, our studies aim to examine the correlation of IDO1 expression and CD8+ T lymphocyte infiltration in colon cancer." (PMID 31391111, 2019). "miRNAs may play an important role in the immune equilibrium of IDO1 and CD8+ T cells in the colon cancer microenvironment." (PMID 31391111, 2019). "Human colon cancer constitutively expressed IDO1 and expressed higher IDO1 levels than did corresponding normal tissues by IHC, as previously reported." (PMID 31391111, 2019). "The protein expression level of IDO1 was higher in colon cancer tissues than that in adjacent noncancerous tissues in patients with colon cancer, which is consistent with previously reports." (PMID 31391111, 2019). "These miRNAs may downregulate IDO1 expression at the posttranscriptional level and affect the CD8+ T cell response in the colon cancer microenvironment." (PMID 31391111, 2019). "Elevated levels of the enzymes TDO2, IDO1, and AFMID combined with the Trp transporters SLC1A5 and SLC7A5 in colon cancer patients may lead to increased Trp and Kyn levels in colon cancer cells." (PMID 31416966, 2019). "Our data demonstrate that overexpression of miR-153 and subsequent IDO1 inhibition do not alter cell proliferation and other cellular processes in colon cancer cells." (PMID 29685162, 2018). "miR-153 directly inhibits IDO1 expression by targeting its 3′ untranslated region in colon cancer cells, yet miR-153 overexpression does not affect colon cancer cell survival, apoptosis, or colony formation." (PMID 30068361, 2018). "miR-153 directly inhibits IDO1 expression by targeting its 3′ untranslated region in colon cancer cells; yet, miR-153 overexpression does not affect cancer cell survival, apoptosis, and colony formation." (PMID 29685162, 2018). "Generally, the effect of IDO1 on tumors depends on its mediate immunoregulatory effect; however, Thaker found that IDO1 directly mediates the proliferation and progression of colon cancer independent of its immunoregulatory effects." (PMID 33718227, 2021). "IDO1 overexpression is also observed in colon cancer cell lines (HCT-116 and HT-29) in absence of an inflammatory environment, suggesting that genetic mutations or epigenetic modification of IDO1 could also be driving colon carcinogenesis." (PMID 33916690, 2021). "However, Thaker reported that IDO1 promotes colon cancer growth directly independent of T cell-mediated immune regulation." (PMID 33718227, 2021). "Interestingly, we observed the lowest OS in group IV*, even though it had high levels of CD8A, whereas Group III* had the most favorable outcomes for colon cancer with higher CD8A expression in the absence of IDO1 expression (P = 0.032)." (PMID 33425745, 2020). "However, the clinical significance of IDO1 expression within primary colon cancer tumors, independent of neoadjuvant radiotherapy and/or chemotherapy, remains incompletely understood." (PMID 33425745, 2020). "Interestingly, it was reported that in human colon cancer, miR-448 could suppress CD8+ T-cell apoptosis and enhance the CD8+ T-cell response by inhibiting indoleamine 2,3-dioxygenase 1 enzyme function." (PMID 32992819, 2020). "Interestingly, high IDO1 protein expression was positively correlated with overall survival in patients with early-stage colon cancer but not in patients with late-stage colon cancer." (PMID 31391111, 2019). "However, there are no reports about miRNA targeting IDO1 in colon cancer and how miRNAs affect the T cell response via IDO1 in the colon cancer microenvironment is less well characterized." (PMID 31391111, 2019). "However, whether IDO1 affects the quantity of tumor-infiltrating T lymphocytes in colon cancer is not clearly defined." (PMID 31391111, 2019).
colon carcinoma (continued). "Compared with miR-448high colon cancer patients, IDO1 level will be elevated faster in these miR-448low colon cancer patients when they receive T cell related therapy (CAR-T, anti-PD-1) due to the lack of endogenous miR-448 inhibition to IDO1." (PMID 31391111, 2019).
colitis (69 papers, 2010 to 2026). Inflammation of the colon. "Specifically, studies in mice revealed that RNase 4 modulates the intestinal microbiome by selectively limiting Parasutterella growth while promoting the indoleamine‐2,3‐dioxygenase 1 (IDO1) pathway and reducing colitis risk." (PMID 41230022, 2025). "In recent studies, it has similarly been found that DSS-induced colitis disrupts tryptophan/kynurenine metabolism through the regulation of the rate-limiting enzyme IDO1, and this phenomenon is closely associated with alterations in the gut microbiota." (PMID 37908541, 2023). "For instance, fecal microbiota transplants from IDO-1-deficient mice directly attenuated the severity of DSS-induced colitis in IDO-1+/+ mice, which suggested that intestinal flora regulated the severity of colitis in Trp metabolism-dependent manner." (PMID 36776388, 2022). "Recently, beta-catenin activation by IDO1 has been demonstrated in an animal model of colitis-associated CRC." (PMID 27578919, 2016). "To further verify that IDO1 might cause M1 macrophage polarization via the GRP78-XBP1 pathway to promote colitis development, we detected the expression of GRP78 and XBP1s in colitis mice." (PMID 40370742, 2025). "Experimental studies further suggest that manipulating this pathway can influence disease severity: IDO1 deficiency attenuates inflammation via downregulation of proinflammatory signaling, whereas its overexpression aggravates colitis through macrophage M1 polarization." (PMID 40572721, 2025). "We demonstrate that Rnase4 acts as an antimicrobial protein, modulating the gut microbiota composition by specifically targeting and killing Parasutterella, thereby enhancing the production of kynurenic and xanthurenic acid through the IDO1 pathway and ultimately reducing colitis susceptibility." (PMID 38987259, 2024). "It is worthy of note that IDO1 expression supported epithelial proliferation independently of the effects on adaptive immunity through the activation of the Wnt/β-catenin signaling pathway in the colitis-associated cancer model (azoxymethane/DSS)." (PMID 33413597, 2021). "In contrast, IDO1-knockout mice are less susceptible to DSS-induced colitis." (PMID 33193381, 2020). "Collectively, studies in humans with IBD and experimental models of colitis suggest that decreased serum tryptophan concentration in dogs with PLE might be due to increased intestinal IDO-1 expression causing increased catabolism of tryptophan." (PMID 31181125, 2019). "Taken together, our data indicate that the severity of DSS-induced colitis development was significantly reduced in Ido1−/− mice and L-1MT administered mice, suggesting that IDO1 deficiency might protect against pro-inflammatory signals." (PMID 26610689, 2015). "This indicates that loss of the functional activity of IDO1 may contribute to reduced expansion of CD11b+Gr-1+ cells including granulocytes in the DSS-induced colitis model." (PMID 26610689, 2015). "Studies have shown that IDO1 could promote colitis-associated tumorigenesis in mice." (PMID 34306038, 2021). "For instance, IDO1–/– mice are more susceptible to 2,4,6-trinitrobenzene sulfate-induced colitis whereas TpH1–/– mice show enhanced protection in response to DSS- or dinitrobenzene sulfonic acid-induced colitis, suggesting that while kynurenine is protective in the gut, 5-HT might be deleterious." (PMID 34540837, 2021). "In addition, IDO1 inhibition resulted in increased mortality and disease severity in an experimental model of T cell mediated colitis, and transfusion of IDO overexpressing DCs was associated with long term allograft survival of recipients in a mouse model of small bowel transplantation." (PMID 32351505, 2020). "AS-IV ameliorated colitis by downregulating IDO1 expression, while upregulating the expression of tryptophan hydroxylase 1 (TPH1), DDC, monoamine oxidase A (MAO-A), and the aryl hydrocarbon receptor (AhR), as well as inhibiting NF-κB p65 phosphorylation." (PMID 42195848, 2026).
colitis (continued). "Colitis mice exhibited elevated hippocampal Ido-1 levels versus N group, which were effectively normalized by AmEVs treatment." (PMID 41496520, 2026). "The results indicated that IDO1 expression was significantly elevated in UC patients and correlated with M1 macrophage polarization observed in both human data and colitis mice." (PMID 40370742, 2025). "Elevated IDO1 expression and kynurenine metabolites have been observed in active colitis, highlighting its role in modulating T-cell responses and sustaining barrier function." (PMID 40572721, 2025). "Despite these promising findings, the therapeutic potential of IDO1 inhibitors such as Indoximod remains insufficiently explored in chemically induced models of acute colitis, particularly in acetic acid-induced colitis." (PMID 40572721, 2025). "Western blotting analysis indicated that IDO1 and iNOS, a molecular marker for M1-polarized macrophage, was significantly increased after induction of colitis." (PMID 40370742, 2025). "To investigate the impact of IDO1 on UC development, we used DSS-induced colitis mice and inhibited IDO1 using 1-MT." (PMID 40370742, 2025). "Activated IDO-kynurenine-AhR axis in IBD mucosa promotes immune tolerance; IDO1 induction or AhR agonists show benefit in DSS-induced colitis." (PMID 41476956, 2025). "Subsequently, DSS-induced colitis was used to measure the level of IDO1, GRP78, XBP1, and M1 marker iNOS correlated with disease activity, while 1MT treatment ameliorated DSS-induced colitis by downregulating IDO1-GRP78-XBP1 pathway." (PMID 40370742, 2025). "The molecular biomarker of murine colitis, Ido1, was reduced 3.7-fold by BM-MSC treatments in the distal colon of Winnie mice." (PMID 38503815, 2024). "We treated Vil Apc Dock2 mice with the IDO1 inhibitor 1-L-MT whilst undergoing repeated rounds of DSS induced colitis." (PMID 39242821, 2024). "Our study provides valuable insight into how Parasutterella promotes colitis; i.e., by suppressing host IDO1 expression and subsequently altering host tryptophan metabolism." (PMID 38987259, 2024). "Collectively, these results suggest that Lys enhances IDO1 expression to confer protection against DSS-induced colitis via AhR activation." (PMID 38351003, 2024). "Apart from infectious diseases, modulation of IDO1 activity has potential in treating various intestinal diseases, such as colitis or inflammatory bowel disease." (PMID 39120289, 2024). "This is the first study demonstrating immunomodulatory activity of IDO1 in a chronic mouse model of DSS-induced colitis." (PMID 36798536, 2023). "As previously demonstrated, the expression of IDO1 in the intestinal mucosa was strongly increased in the acute phase of DSS-colitis (day +7); however, the protein level returned rapidly to basal levels during the recovery period." (PMID 36798536, 2023). "The expression and secretion of human interferon-γ and KYNA combined livestock treatment HADSCs promote indoleamine 2,3-dioxygenase-1 (IDO-1) signaling, effectively improving the fibrosis of colitis and colon." (PMID 37020597, 2023). "Our results demonstrate that IDO1 expression and activity closely follow disease activity, with a rapid increase during the acute phase of the colitis, and lower levels during recovery and a second DSS challenge." (PMID 36798536, 2023). "In this study, we found that the Kyn pathway was significantly activated in the cerebral cortex after DSS-induced colitis, which was manifested by the significant elevation of Kyn and IDO-1." (PMID 36776388, 2022). "Treatment with CAip and CAig reduced the level of kynurenine, kynurenic acid and other downstream metabolites, and even downregulated the expression of IDO-1 in colitis mice." (PMID 36741371, 2022). "hADSCs treated with IFN-γ and KYNA significantly upregulated the expression and secretion of IDO-1, which has effectively ameliorated CD pathology-like colitis injury and fibrosis." (PMID 36076306, 2022).
colitis (continued). "In colonic mucosa of UC patients, IDO-1 expression was significantly higher in UC-active/UC-inflamed patients compared with Control or UC-remission/UC-uninflamed patients, which reflected that colitis induced the activation of IDO-1 in colon." (PMID 36776388, 2022). "Collectively, these results demonstrated the increase of IDO-1 in UC patients and colitis mice, indicated upregulation of Kyn pathway." (PMID 36776388, 2022). "Inflammatory cytokines IFN-γ- and KYNA-treated hADSCs more effectively alleviate TNBS-induced colitis and colonic fibrosis through an IDO-1-dependent manner." (PMID 36076306, 2022). "The upregulation of IDO1 is observed not only in the experimental murine colitis but also from the clinical samples of human IBD." (PMID 33413597, 2021). "Kynurenine generated by IFNγ-stimulated IDO1 induction increases IL-10R1 expression on intestinal epithelia cells, resulting in the mitigation of colitis." (PMID 33430497, 2021). "Clinically, IDO1 mRNA expression has been correlated with colitis severity, peri-tumoral immune tolerance, and worse survival in CRC patients." (PMID 33065994, 2020). "Noteworthy, transcripts of IL-18 binding protein and IDO1 were highly downregulated in Ccr8−/− mice with colitis." (PMID 33613532, 2020). "We found that Tα1 protects mice from anti–CTLA-4–induced colitis by engaging the IDO1 tolerogenic pathway in the gut, while sustaining the antitumor activity via DCs and lymphocyte infiltration at the tumor site." (PMID 32817121, 2020). "Deficiency or inhibition of IDO1 aggravates 2,4,6-trinitrobenzene sulfate (TNBS)-induced colitis in mice." (PMID 33193381, 2020). "IDO1 and IDO2 are functional interacting partners and have been associated to various autoimmune states, such as colitis, arthritis and encephalomyelitis." (PMID 29510755, 2018). "IDO1 also attenuates intestinal inflammation in other models of colitis, including graft vs. host disease and the Citrobacter rodentium infection model." (PMID 30697218, 2018). "The expression of IDO1 is also higher in murine models of experimental colitis and has been shown to regulate inflammatory response." (PMID 30697218, 2018). "In the mouse model of DSS induced colitis, IDO1 increased levels of pro-inflammatory chemokines and cytokines." (PMID 29284484, 2017). "Conversely, another study reported that local increases in IDO1 production during active inflammatory responses resulted in more severe colitis promoted by key mediators of pro-inflammatory signaling." (PMID 26610689, 2015). "This suggests that the differences in colitis development between Ido1−/− and Ido1+/+ mice result from dysregulation of the TLR-MyD88 signaling pathway." (PMID 26610689, 2015). "One of the potential approaches is to study the roles of IDO1 using dextran sulfate sodium (DSS) which induces colitis by disrupting epithelial barrier function of colon tissues." (PMID 26610689, 2015). "The most striking result was that expression of the majority of genes involved in TLR signaling was down-regulated in DSS-treated Ido1−/− mice, suggesting that TLR signaling is essential for the contributions of IDO1 to the development of DSS-induced colitis." (PMID 26610689, 2015). "A contradictory effect of IDO1 on inflammatory responses during the development of colitis was recently described." (PMID 26610689, 2015). "By using DSS-induced experimental colitis mice models, we found that the disease in Ido1−/− mice was less severe than in Ido1+/+ mice." (PMID 26610689, 2015). "We determined the effects of Ido1 expression on colitis-related clinical parameters and histopathological damage." (PMID 26610689, 2015). "These gene expression signatures suggested that Ido1−/− mice would be less likely to develop severe colitis than Ido1+/+ mice." (PMID 26610689, 2015). "Increased IL-18 and Ido1 levels have been shown to play a protective role in mice during experimental colitis." (PMID 26456940, 2015).
colitis (continued). "The IDO1 enzyme is secreted by intestinal epithelial and immune cells to convert tryptophan into downstream metabolites that contribute to gut homeostasis and prevent colitis." (PMID 41230022, 2025). "To further validate our hypothesis, we established a DSS-induced colitis model and evaluated the effects of IDO1 inhibition through oral administration of 1-MT." (PMID 40370742, 2025). "Moreover, studies have shown that acetic acid-induced colitis upregulates the IDO1/kynurenine axis, and agents like sodium selenite that inhibit this pathway effectively reduce mucosal inflammation and preserve epithelial integrity." (PMID 40572721, 2025). "However, when IDO1 was inhibited by 1-MT, the colitis severity was significantly ameliorated with a marked decrease in the expression levels of both GRP78 and XBP1s." (PMID 40370742, 2025). "The results indicated that 1-MT-mediated inhibition of IDO1 alleviated colitis severity." (PMID 40370742, 2025). "However, the expression of both M1 makers and IDO1 was significantly downregulated after treatment with 1-MT in DSS-induced colitis mice." (PMID 40370742, 2025). "It has been shown that IDO-1 gene expression is upregulated in the mPFC of mice with colitis." (PMID 38247868, 2024). "Along these lines, induction of IDO1 affects colitis severity." (PMID 39242821, 2024). "Because 4-MOV showed no protective effect against DSS-induced colitis, we chose to focus on the potential role of Lys in modulating IDO1-driven Trp metabolism." (PMID 38351003, 2024). "Thus, we are trying to generate Gpr43−/−-Ido1−/− double knockout mice to confirm that these two immunomodulatory factors synergistically regulate Treg/Th17 responses in DSS-induced colitis." (PMID 38351003, 2024). "Likewise, AT-MSCs induced with IFN-γ and kynurenic acid substantially upregulated the expression and secretion of IDO-1, finally alleviating CD pathology-like colitis injury and fibrosis in vivo." (PMID 36707899, 2023). "It has been shown that the pharmacologic modulation of IDO1 activity can affect the symptoms of acute colitis.25, -27 Therefore, we investigated whether the modulation of IDO1 activity could affect the late phase of colitis." (PMID 36798536, 2023). "We found that IDO-1 mRNA levels were significantly higher in peripheral blood mononuclear of UC patients but not CD patients compared with the normal group, which indicated that colitis induced the activation of IDO-1 in immune cells." (PMID 36776388, 2022). "In DSS-induced colitis mice, we found a significant increase in serum Kyn level and a significant decrease in serum Kyna level, which was mediated by the rate-limiting enzymes IDO-1 and KAT2." (PMID 36776388, 2022). "Notably, the ability of hADSCs with IDO-1 knockout to treat colitis was significantly impaired and diminished the protective effects of the primed hADSCs with IFN-γ and KYNA." (PMID 36076306, 2022). "Indeed, increased IDO-1 gene expression was observed in the medial prefrontal cortex (PFC) of mice with colitis, however, this was accompanied by reduced microglia expression." (PMID 34983592, 2022). "We tried to find out whether the IFN-γ and poly(I:C)-primed MSCs have better therapeutic efficacy on the experimental colitis in the IDO1-dependent manner." (PMID 33413597, 2021). "Furthermore, overexpression of IDO1 in the intestinal epithelium augments resistance to colitis via the promotion of secretory cell differentiation and mucus production." (PMID 33430497, 2021). "In agreement with previous studies, IDO1-deficient mice were not more susceptible to DSS-induced colitis." (PMID 32817121, 2020). "However, IDO1 levels in the intestine are higher in patients with IBD, although the role of IDO1 in colitis is somewhat controversial." (PMID 32617076, 2020).